APOE (apolipoprotein E)
Diseases named in the same sentence as APOE in open-access papers (continued):
Sharing a sentence is not in itself a finding about the gene and the disease.
diabetes (continued). "For a more systemic indication of endothelial activation in response to diabetes, we measured soluble VCAM-1 (sVCAM-1) in plasma from wt, ApoE−/− and ApoE−/−/TNFα−/− mice." (PMID 20856927, 2010). "Comorbidities, particularly cardiovascular and renal disease, diabetes, metabolic syndrome, cancer, dysimmune or chronic inflammatory diseases, and the role of the Apolipoprotein E (ApoE) genotype are not well-defined." (PMID 40924766, 2025). "In addition, APOE ε4 carriers had a 2% higher longitudinal PDSR (95% CI 0–3%, p = 0.045), which persisted after adjusting for CVD and diabetes, but was attenuated to 0% in Model 2 and to 1% after adjusting for diabetes (Model 5)." (PMID 38509472, 2024). "For instance, in AD patients with a non-insulin-dependent diabetes mellitus diagnosis, our analysis revealed lower average PRS scores compared to individuals with only AD, either including or excluding APOE (t-test = −4.26, P = 2.3e-5 and t-test = −2.88, P = 4.01e-3, respectively)." (PMID 39371139, 2024). "Nonetheless, the created hybrid model included all variables of the CAIDE model as well as history of head injury, depression, diabetes mellitus, smoking status, alcohol consumption, social activity, cognitive activity, fish intake, history of coronary artery disease (CAD), and APOE ε4." (PMID 38570813, 2024). "Since the models were attenuated after adjusting for CVD, diabetes and hypertension, the benefits which stem from ε4 carriage are reduced as an individual starts to develop APOE ε4 related negative outcomes." (PMID 38509472, 2024). "a Conversely, in obese individuals with diabetes, IR may trigger an increase in very low-density lipoprotein (VLDL)-induced APOE production." (PMID 38956564, 2024). "Thus, we conclude that cardiac dysfunction develops in diabetic ApoE-/- mice, arising from inflammation, necroptosis, and adverse tissue remodeling, which is ameliorated by MSC-Exos, a potential therapeutic for diabetes-induced cardiomyopathy." (PMID 38390337, 2024). "There are other factors that may impact gut-brain interactions in aging, such as apolipoprotein E (APOE) variance, diet, body mass index (BMI), obesity, and diabetes." (PMID 37736325, 2023). "Recent research has highlighted the critical role of the gut microbiome in modulating brain functions during aging, which can be influenced by various factors such as apolipoprotein E (APOE) genetic variance, body mass index (BMI), diabetes, and dietary intake." (PMID 37736325, 2023). "These participants tended to be older, had lower levels of education, and included more APOE ε4 carriers; more of them had a baseline history of CVD, hypertension, insulin use, longer duration of diabetes, higher average HbA1c levels, and reported more depressive symptoms." (PMID 37457508, 2023). "ApoE phenotype-dependent concentrations of total apoE, apoB-100, apoC-I and LDL-cholesterol were investigated in a subgroup of CAD patients on statin therapy (N = 100), as well as in CAD patients with diabetes (N = 86)." (PMID 35745204, 2022). "Thus, our results indicated that ototoxicity by diabetes and/or dyslipidemia accelerated ARHL in ApoE KO mice, thereby suggesting the importance of appropriate treatment of patients with diabetes and/or dyslipidemia to prevent ARHL." (PMID 36408520, 2022). "GCG, IRS1, VEGFA, STAT3, CCL2, CASP3, and APOE are the 7 DEPs that are related to diabetes mellitus as specific proteins but not seen among the central proteins of fatty liver disease." (PMID 35154608, 2021). "We also revealed interactions of physical inactivity with TOMM40 G, and diabetes with TOMM40 G independent of the APOE polymorphism, such that TOMM40 G in combination with either physical inactivity or diabetes was associated with a lower MMSE score." (PMID 33790814, 2021).
diabetes (continued). "APOE genotypes affect IHD risk increasingly from ε2ε3, ε3ε3, ε3ε4 to ε4ε4, with similar patterns for pulse pressure and plasma apoB, but not for diabetes." (PMID 33927215, 2021). "Since MCD-fed mice recapitulate the histology of human NAFLD (hepatic steatosis, and fibrosis) but lack the metabolic component (obesity, high cholesterol and diabetes) to assess the impact of metabolic imbalances in NLRP3 activation in NASH, ApoE-/- mice were fed with WD." (PMID 34513923, 2021). "To date, no studies have evaluated the association between ApoE and PAD in Chinese type 2 diabetes mellitus (T2DM) patients." (PMID 32211081, 2020). "The analysis of Oil Red O stained area showed that acacetin treatment significantly decreased the aorta lesion area from 11.0 ± 1.12% (n = 11, p = 0.0014 vs. control) in non-treated STZ-diabetic ApoE−/− mice to 7.0 ± 0.6% (p = 0.0071 vs. STZ-diabetes)." (PMID 33519472, 2020). "Differential APOE genotype effects have also been reported for the treatment of mild-to-moderate AD patients using the diabetes drug rosiglitazone, with APOE4− AD patients, but not APOE4+ AD patients, showing cognitive improvement." (PMID 33148345, 2020). "Western diet feeding also promoted mesangial expansion in apoE KO mice (p < 0.05), although not to the same degree observed with diabetes." (PMID 32581831, 2020). "The link between SM and diabetes has not been clearly elucidated, but previous data have shown that clearance synthesis and apoptosis in apoE knockout mice result in increased SM content in lipoproteins." (PMID 30835753, 2019). "The MoCA scores and the current state and history of disease, including hypertension, diabetes mellitus, and hyperlipidemia, were not different among the APOE groups." (PMID 30984391, 2019). "The selected features of the proposed classifier on the Set 1 were CETP TaqIB [rs708272], CETP A373P [rs5880], LPL D9N [rs1801177], ApoE, ABCAI R1587K [rs2230808], APOA5 C-1131T [rs662799], LPL HindIII [rs320], APOC3 SstI [rs5128], family history of obesity, and diabetes, and APOA1 MspI [rs2893157]." (PMID 30026888, 2018). "In another study, dapagliflozin did not change the weight of APOE(−/−) mice, with or without diabetes while ipragliflozin 1 mg/kg/day for 4 weeks, reduced significantly the weight of db/db rats." (PMID 30049285, 2018). "Some clinical information did not relate with APOE gene polymorphisms as shown in the present study, including age, gender, BMI, HDL, and history of hypertension, diabetes, dyslipidemia." (PMID 29074556, 2017). "Diabetes, which only affected a small number of patients, was not linked to increased WMH volume or to APOE genotype." (PMID 25984242, 2015). "Sensitivity analyses were performed to control for potentially confounding variables: smoking, education, childhood IQ (LBC1921 and LBC1936 only), social class (LBC1921 and LBC1936 only), APOE (LBC1921, LBC1936, and NAS only), cardiovascular disease, high blood pressure, and diabetes." (PMID 25633388, 2015). "Already early after the onset of diabetes, circulating monocytes were elevated in diabetic ApoE−/− mice when compared to non-diabetic controls, as evidenced by higher percentages of CD115 (M-CSF receptor) expressing blood mononuclear cells." (PMID 23755169, 2014). "Up till now, however, it is not clear if APOE ε4 carriership has a similar effect in younger persons with diabetes." (PMID 24367577, 2013). "Diabetes-induced endothelial activation in ApoE−/− mice seems driven by elevated plasma triglycerides but not by cholesterol." (PMID 20856927, 2010). "As a complementary approach to evaluate a potential endothelial dysfunction in response to diabetes, the expression of VCAM-1, ICAM-1, P-selectin and E-selectin mRNA was measured in intact retinas of wt, ApoE−/−, TNFα−/− and ApoE−/−/TNFα−/− mice by real time RT-PCR." (PMID 20856927, 2010).
diabetes (continued). "For example, overexpression of IL-10 in islet cells in a nonobese diabetic mouse model exacerbates diabetes and, recent data indicate that ApoE can stimulate dendritic cells to present lipids." (PMID 20445733, 2010). "This diabetes-induced ICAM-1 expression in ApoE−/− mice was not accompanied by increased levels of pro-inflammatory cytokines in retina, nor with elevated sVCAM levels, suggesting a different scenario than that found in diabetic wt mice." (PMID 20856927, 2010). "Diabetes-induced endothelial activation in ApoE−/− mice seems driven by elevated plasma triglycerides and not by cholesterol." (PMID 20856927, 2010). "There was little evidence for an interaction between APOE ε4 and hypertension, diabetes or heart disease." (PMID 20576093, 2010). "Comparative analysis failed to indicate a significant difference among APOE groups and age (p = 0.28), gender (p = 0.13), diabetes (p = 0.81) and smoking status (p = 0.66)." (PMID 21059196, 2010). "The final multivariate models included APOE variants, age, sex, education, ever/never smoking, HDL cholesterol, CRP, triglycerides, TSH, diabetes, hypertension, obesity and albuminuria." (PMID 19852818, 2009). "High incidence of disease in North Indian population and lack of study exploring the genetic basis of diabetes made us to study the association of CETP TaqI B and D442G; and APOE HhaI polymorphisms with T2DM." (PMID 15992403, 2005). "ApoE knockout mice were divided into early diabetes (dosed from 10 to 22 weeks of age), late diabetes (dosed from 18 to 30 weeks of age), and non-diabetic groups after streptozotocin treatment, and each group received semaglutide, tirzepatide, or saline for 12 weeks." (PMID 41946762, 2026). "No statistical difference was observed between the non-MRI and MRI samples regarding demographic factors, APOE ε4 status, smoking status, alcohol consumption, physical activity, BMI, total cholesterol level, hypertension, diabetes, depression, verbal fluency, balance, and chair stand." (PMID 39642342, 2025). "n/n (%) values for hypertension, diabetes, hypercholesterolemia, and APOE ε4 status first present the number of participants without the risk factor, then the number of participants with the risk factor, followed by the proportion of participants (%) with the risk factor." (PMID 40682084, 2025). "Similarly, APOE ε4 carriers had a 5% higher LVmass p = 0.057 which was increased to 6% after adjusting for CVD (p = 0.040) or hypertension (p = 0.040), and to 7% after adjusting for diabetes (p = 0.024)." (PMID 38509472, 2024). "However, there were no sex-related differences in monthly income, history of diabetes, APOE genotype, or MET." (PMID 37248457, 2023). "Both male and female 16-week-old agouti KKAy+/–ApoE–/– mice revealed non-fasted blood glucose levels >250 mg/dl, reflective of diabetes, with greater than 2-fold increase in glucose levels noted in these animals compared to age- and sex-matched non-agouti KKAy–/–ApoE–/–." (PMID 36505365, 2022). "A total of 162 participants in the high-PP group were matched with the same number in the low-PP group as a control based on age, sex, education, smoking, drinking, lack of exercise, hypertension, diabetes, dyslipidemia, cardiovascular disease and APOE ε4 carriage." (PMID 36552151, 2022). "While we could not stratify on ApoE genotype, we analyzed metformin initiation, which failed to provide significant benefit to users, despite the shorter diabetes duration." (PMID 34857046, 2021). "While TZD may accelerate memory decline in ApoE-ε4 non-carriers with AD and diabetes, we did not have access to such data." (PMID 34857046, 2021). "Indeed, diabetes was associated with a 2.5-fold increase in expression compared to chow fed C57BL/6 mice (p < 0.0001), an effect not observed in apoE KO mice." (PMID 32581831, 2020).
diabetes (continued). "While age and apolipoprotein E (APO-E) status represent nonmodifiable risk factors for this disease, diabetes, midlife hypertension, obesity, depression, smoking habits, cognitive inactivity, and low education are some of the known potentially modifiable factors." (PMID 31295866, 2019). "After adjusting for age, sex, years of education, APOE-ε4 genotype, BMI, depression, diabetes, hypertension and stroke, the non-matched models indicated that the OR of high LDL-C level (OR [95%CI] = 0.56[0.30, 1.04]) had an upper limit awfully close to the null threshold." (PMID 30483213, 2018). "In addition, statistical analysis demonstrated that the polymorphisms of APOE, BDNF, GRIN2B, and HSP70-1 genes are not related with hypertension, diabetes, low blood pressure, and vascular disease." (PMID 25893192, 2015). "However, when mRNA levels of VCAM-1, ICAM-1 and E-selectin were studied in isolated retinal vessels from ApoE−/− using the same assays as for intact retina, a clear increase of ICAM-1 in response to diabetes was observed (p<0.05) and similar trends were seen for VCAM-1 and E-selectin (n.s.)." (PMID 20856927, 2010). "Although our study found abnormal lipid profile in diabetes patients and its association with complications like diabetic neuropathy and retinopathy, yet these lipid profile abnormalities did not correlate with CETP TaqI B or APOE HhaI polymorphisms." (PMID 15992403, 2005). "In addition, we found a marginally significant association of TOMM40 with cognitive performance independent of the APOE gene and further detected interactions between VRFs (e.g., physical inactivity, diabetes, and aggregated VRFs) and TOMM40 G but not for the APOE ε4 variant." (PMID 33790814, 2021). "Among 5730 Hispanic/Latino adults (mean [SD] age = 63.5 [8.2] years, 54% female), education, Hispanic/Latino background, diabetes, hypertension, dyslipidemia, and CKD status varied by age group, while sex, BMI category, or APOE ε4 genotype did not." (PMID 41398079, 2025). "Models showed this adjustment successfully eliminated effects of eGFR, BUN, and diabetes on plasma levels, with no compromise to model estimates of known AD-related factors (effect sizes for ADD and APOE ε4 were modestly/non-significantly increased)." (PMID 40894158, 2025). "Upon STZ-induced diabetes, apoE KO mice revealed increased renal NO (0.51 ± 0.16 in diabetic apoE KO mice vs 0.29 ± 0.12 pmol MNIC / mg tissue in non-diabetic apoE KO, P<0.01)." (PMID 28103268, 2017). "However, the mechanism of BRG1 in regulating diabetes-related macrovascular cardiovascular atherosclerosis and Ang II induced AAA formation under ApoE gene knockout condition remain not to be proved." (PMID 33330454, 2020).
Hypertension (583 papers, 2003 to 2026). The presence of chronic increased pressure in the systemic arterial system. "Risk factors for CAA development include aging, hypertension, and carrying specific alleles of the apolipoprotein E (ApoE) gene." (PMID 40867593, 2025). "In the present study, we analysed a larger sample (n = 147 for ad) with extensive adjustments for potential confounders, including age, sex, education level, nutritional risk, hypertension history and APOE genotype." (PMID 40717521, 2025). "TMT was positively correlated with Montreal Cognitive Assessment‐Basic (MoCA‐B) scores (r = 0.124, p = 0.001), independent of confounders such as age, sex, education level, nutritional risk, history of hypertension and apolipoprotein E ε4 genotype." (PMID 40717521, 2025). "Factors that increase hemorrhagic risk are older age, already recurrent ICH, lobar ICH, higher number and lobar location of CMBs, CAA (especially when with cSS), uncontrolled hypertension and ApoE ε2 allele." (PMID 41157242, 2025). "Apolipoprotein E (APOE) gene polymorphisms were associated with coronary atherosclerosis and hypertension." (PMID 39261765, 2024). "The interactive association between Aβ burden and hypertension status on EC tau was confirmed in a linear regression model adjusting for age, sex, and APOE ε4 status using a continuous Centiloid variable (β = 0.007, p = .002)." (PMID 39254220, 2024). "Studies have indicated that BBM levels tend to increase with age and are elevated in individuals with APOE ε4 allele, chronic kidney disease, hypertension, stroke, myocardial infarction and higher body mass index." (PMID 39044504, 2024). "Numerous studies have provided evidence suggesting that the existence of the APOE ε4 allele (rs429358) is correlated with a heightened susceptibility to the development of hypertension." (PMID 38540308, 2024). "Patients with SSNHL had a higher risk of concomitant hypertension and elevated atherosclerogenic lipid levels, with apolipoprotein B and apolipoprotein E identified as independent risk factors for the onset of SSNHL." (PMID 38714080, 2024). "Logistic regression analysis was performed to evaluate the interactions between ApoE polymorphisms and various factors, such as age, sex, and prevalence of hypertension in patients with T2DM." (PMID 37123009, 2023). "From this point it is significant that aging is associated with increasing ApoE levels, it leads to increased NF-kB activity in cerebral vessels, and aging and hypertension interact to promote increased MMP-9 activity and formation of cerebral microbleeds." (PMID 38073626, 2023). "There were no significant sex differences in mean age, the distribution of APOE ε4 allele, stroke, hypertension, daily ActiGraph wear time, and serum concentrations of IL-6, IL-8, and TNF-α." (PMID 37491244, 2023). "A meta-analysis investigating the association between APOE polymorphisms and hypertension showed that the APOE ε4 allele and the genotypes ε3/ε4 and ε4/ε4 are risk factors for hypertension." (PMID 37510094, 2023). "Extensive studies have been performed to investigate the relationship between apoE polymorphism and hypertension." (PMID 36551995, 2022). "The current study assessed the joint effects of hypertension and APOE ε4 risk genes on cognitive function in a large sample of elderly people." (PMID 35624902, 2022). "The association between APOE rs429358 genotypes and hypertension was studied using three genetic modes: co-dominant mode (T/C vs. T/T, C/C vs. T/T), dominant mode (T/C plus C/C vs. T/T), and recessive mode (C/C vs. T/T plus T/C)." (PMID 36158751, 2022). "The APOE polymorphism is a risk factor, not only for AD, but also for dilated cardiomyopathy and hypertension." (PMID 35562955, 2022). "Continued follow-up of this sample will help to further elucidate the neural mechanisms underlying the association between APOE and hypertension." (PMID 35624902, 2022).